IL1B (interleukin 1 beta)
Diseases named in the same sentence as IL1B in open-access papers (continued):
Sharing a sentence is not in itself a finding about the gene and the disease.
infection (continued). "Additionally, we found using quantitative real-time PCR that application of β-glucan significantly enhanced the expression of Toll-like receptor (TLR) 2, interleukin (IL)-1β and iNOS at 2 dpi (days post infection) and reduced the increase of TLR2, IL-1β and iNOS induced by Leptospira at 5 dpi." (PMID 31675378, 2019). "However, further sub-classification of patients demonstrated that IL-1β positively correlated with IL-17 during infection of NSM patients but not SM patients, although both groups exhibited similar levels of these cytokines." (PMID 31620120, 2019). "The cleaved/activated Caspase-1, cleaved/activated IL-1β, and IL-18 were significantly induced in human corneal epithelial cells following infection with virulent laboratory strains of HSV-1, McKrae and 17, as early as 2 h post-infection, compared to control β-actin (P < 0.05)." (PMID 31367214, 2019). "The hypothesis that patients with DWWS have decreased levels of IL-1β could be considered, but given the lack of infection control, the levels increase again." (PMID 30901375, 2019). "MCC950-treated IL-1β+/+ and untreated IL-1β-/- mice showed less weight loss and mortality, reduced IFN-γ and total protein levels, as well as leukocyte number in BAL, as compared to IL-1β+/+ mice without MCC950 treatment on day 5 post-infection." (PMID 30964929, 2019). "Infection with SA-induced or PA-induced high production of IL-1β, IL-23, and TGF-β in nasal epithelial cells, whereas no IL-33 or TSLP could be detected." (PMID 31089134, 2019). "Therefore, IL-1β, CCL2, and CCL3 may be useful biomarkers for tracking infection and determining when antibiotic treatment could be terminated as well as for diagnosis, although additional studies are needed to validate this possibility." (PMID 31262978, 2019). "MEKi did not modulate production of IL-1β or IL-6 following RV2 or RSVA2 infection." (PMID 31319869, 2019). "Three days post-infection, the E. coli challenge significantly increased the expression of nuclear factor-κB (NF-κB), peroxisome proliferator-activated receptor-γ (PPAR-γ), toll-like receptor 4 (TLR4), IL-1β, and IL-6 (P < 0.05) and tended to increase the expression of TNF-α (P = 0.052)." (PMID 29948799, 2019). "On average 5.6 times more IL1B mRNA (p < 0.001), 5.2 times more IL6 mRNA (p < 0.001), 4.3 times more TNF mRNA (p < 0.001) and 48.5 times more IFNG mRNA (p < 0.001) were produced by bMDM pre-treated with NTC siRNA in response to AF2122/97 infection than G18 infection." (PMID 31527895, 2019). "However, pre-infection of cells with S. pneumoniae does not inhibit the induction of Pro-IL-1β or TNFα by the TLR ligand LPS, thus ruling out priming as the target of S. pneumoniae-mediated inflammasome inhibition." (PMID 31375698, 2019). "However, due to the high degree of variability in the amount of IL-1β released by bMDM from different animals in response to G18 infection, the amount produced was not statistically significantly different from that of uninfected cells." (PMID 29263113, 2018). "The authors suggested that IL-1β produced by activated microglia may trigger IRF3 activity in astrocytes to amplify innate immune responses and provide a second line of defense against infection in the CNS." (PMID 29559569, 2018). "The hepatic levels of TNF, IL-6, IL-1β, and IL-12p70 did not change significantly upon infection." (PMID 29568732, 2018). "Collectively, these findings indicate that infection with T. gondii alone is not sufficient to induce inflammasome activation because priming signals are needed for IL-1β mRNA expression, but when combined with LPS, it provides a signal that drives IL-1β release." (PMID 30154263, 2018). "Changes in cytokine expression in response to infection by Campylobacter at 20 da in TLG2 birds was characterized in the ileum tissues by a significant (p < 0.05) increase in most of the cytokine expression at 15 dpi compared to uninfected TLG1 birds, with the exception of IFN-γ and IL-1β." (PMID 29753324, 2018).
infection (continued). "Therefore, it seems that IL-1β production through ATF3-mediated ROS inhibition is necessary to prevent the inhibition of primed NLRP3, as a sufficient amount of ROS was secreted during infection in the case of gram-positive bacteria." (PMID 30214444, 2018). "To test this hypothesis, we screened supernatants from infected cell cultures 24 h post-HSV1716gfp infection (MOI 3) for candidate molecules including adenosine triphosphate (ATP), HMGB1, type 1 interferon (IFN-⍺, IFN-β), interleukin 1-β (IL-1β), and oncostatin M." (PMID 29543735, 2018). "Moreover, infection did not significantly alter IL-1β levels in the PeLF of non-diabetic animals, but it did promote an increase in PeLF IL-1β in diabetic animals (DATCC)." (PMID 30705678, 2018). "Having established that IL-1β production is enhanced during GAS infection in an SLS-dependent manner, we next wanted to determine whether the production or activity of this cytokine could be influenced by inhibitor delivery during infection." (PMID 30018884, 2018). "Because intraperitoneal injection of the IL-1β targeting therapies produced minimal changes in GAS-induced tissue damage, we hypothesized that greater efficacy might be achieved by administering these treatments directly at the infection site." (PMID 30018884, 2018). "The secretion of certain pro-inflammatory cytokines including IL-1β by macrophages and dendritic cells can be induced by RIPK3 under certain conditions, with Ripk3 deletion attenuating inflammasome activation and IL-1β processing following LPS stimulation or infection with certain RNA viruses." (PMID 29892302, 2018). "Notably, infection of C. glabrata, unlike that of S. cerevisiae and C. albicans, is known to induce reduced production of IL-6, IL-8, TNFα, IL-1β, and IFN-γ in human monocyte-derived macrophages." (PMID 29491142, 2018). "To study the influence of Candidalysin on inflammasome activation, we measured IL-1β secretion by LPS-primed primary hMDMs after infection with Wt C. albicans and mutants lacking the entire ECE1 gene (ece1Δ/Δ) or only the Candidalysin-encoding sequence (ece1Δ/Δ + ECE1Δ184–279)." (PMID 30323213, 2018). "Our results showed that topical LTB4 decreased lesion size and bacterial clearance in macrophage-depleted mice, restored production of the chemokines, CCL2 and CXCL4, but not CXCL2, VEGF, IL-33, and IL-1β and neutrophil migration to the site of infection in DT-treated MMDTR mice." (PMID 30102746, 2018). "Expression of an array of cytokines (CSF3 [G-CSF], IFNγ, IL-1β, IL-6, IL-22, IL-17A, and IL-10), chemokines (CCL20, CXCL2 and CXCL9) and receptors (CD40) known to be involved in the regulation of S. pneumoniae inflammatory response was measured at 0, 6, 24, and 48 h post-infection." (PMID 30333823, 2018). "IL-1β mRNA expression was not significantly altered by infection with C. suis." (PMID 29973271, 2018). "Quantification of IL-1β production in the skin of the infected mice revealed that by 72 h post-infection, none of the treatments delivered intraperitoneally were effective at reducing IL-1β levels compared to infected mice treated with only vehicle controls (Flaherty, data not shown)." (PMID 30018884, 2018). "Therefore, inhibition of microglial IL-1β and astrocytic 5-HTT, or specific activation of 5-HT1A receptor could be promising ways to ameliorate the various symptoms of CFS, at least in infection-related cases." (PMID 30505285, 2018). "The anti-infection defense of recombinant L. monocytogenes that enhanced the inflammasome activation is due to caspase-1-induced pyroptosis, but not due to the secretion of IL-1β and IL-18." (PMID 28468643, 2017). "To explore the possibility that cysteamine may control the increased production of inflammatory cytokines by BMDMs from CftrF508del/F508del mice following P. aeruginosa infection, we measured the levels of IL-1β and TNF-α in culture supernatants from BMDMs collected after 24 h following infection." (PMID 28079883, 2017).
infection (continued). "Indeed, whereas cultured pearl BMDCs secreted ~50% less IL-1β than WT DCs in response to STm infection, there was no impairment in STm-stimulated IL-1β secretion by bone marrow-derived macrophages (BMMΦs) from pearl mice." (PMID 29253868, 2017). "In particular, the pronounced degree of adaptation observed for Il1b and Il6 in vivo suggested that additional negative feedback constraints may enforce adaptive recovery to infection or insult in the CNS." (PMID 28855862, 2017). "Masp2−/− mice had significantly lower brain levels of interleukin (IL)-1β (median 3.46 vs. 5.33 ng/mg tissue, P = 0.045), IL-10 (1.04 vs. 1.70 ng/mg tissue, P = 0.038), and TNF-α (9.32 vs. 22.58 ng/mg tissue, P = 0.025) compared to WT mice at 30 h after infection." (PMID 28086930, 2017). "However, the source and role of IL-1β in the early phase of infection before granuloma formation has not been documented." (PMID 28747644, 2017). "In the context of epithelial cells, LPS transfection of IEC led to HMGB1 release and infection of gingival epithelial cells with Fusobacterium nucleatum drove release of HMGB1 alongside Asc and IL-1β secretion, suggesting that inflammasomes may be involved in the active secretion of HMGB1 from IEC." (PMID 28979266, 2017). "In serum, no significant modulation of the IL-1β level was observed for the Finistere infection." (PMID 28241868, 2017). "The non-canonical inflammasome is essential for pyroptosis and IL-1β maturation in response to infection with certain gram-negative bacterial pathogens, or the delivery of cytoplasmic LPS, and occurs as a consequence of the caspase-11 dependent cleavage of gasdermin-D (GSDMD) and pannexin-1." (PMID 28570638, 2017). "Pretreatment of the infected rat models with doses of the traditional energy tonic (100 and 20 mg/mL/kg body weight) before infection nonsignificantly increased cytokines secretion (IL-1β, IL-2, IL-10, IL-13, IFN-γ, and RANTES), while others did not change when compared to those with infection only." (PMID 28408939, 2017). "As we identified no detectable infection driven expansion of vaccine-specific CD4+ T cell populations during the four day culture, we proceeded to investigate whether we could detect infection specific cytokine response (IFN-γ, IL-1β, IL-6, IL-10, IL-12p70 and TNF-α) in the culture supernatant." (PMID 28588268, 2017). "In addition, THP-1, a human monocyte cell line, secreted IL-1β upon infection by F. pedrosoi hyphae, but not conidia." (PMID 29209318, 2017). "Notably, in the absence of infection, pregnant uninfected mice overexpressed lung neutrophil-recruiting chemokines (KC, 1.37 times higher) and cytokines (IL-1β, IL-6 and G-CSF; 1.64-, 7.6- and 3-times higher respectively) relative to non-pregnant controls." (PMID 29176767, 2017). "THP-1 cells were, therefore, stimulated with 1 μg/ml LPS, a concentration mimicking an infection from Gram-negative bacteria, in the presence or absence of 100 μg/ml bLf, and production of IL-6 and IL-1β as well as expression of Fpn, TfR1, Ftn, and Cp-GPI was assessed." (PMID 28663751, 2017). "The increased expression of pro-inflammatory interleukins and chemokines (e.g. interleukins, IL-8; IL-7; IL-1β; and C-X-C motif chemokine 10, CXCL10) parallels the transcriptional response of adult frog skin to the chytrid fungus Batrachochytridium dendrobatidis (BD) infection and entry." (PMID 28462779, 2017). "In addition, in mouse macrophages IL-1β is not induced by L. (L.)amazonensis; however, in vivo IL-1β is important to murine infection control." (PMID 28241012, 2017). "Mice that were immunized with plasmids encoding Leader-Gag and Env and the cytokines IL1β, IL12, IL15, IL28A or GM-CSF, but not Leader-Gag and Env without any cytokine, showed significantly reduced viral loads upon a high-dose Friend virus challenge infection." (PMID 28449719, 2017).
infection (continued). "Since IL-1β and SAA1 enhance each other’s production, we propose that a feed-forward mechanism in terms of IL-1β and SAA1 synthesis may exist in the amnion in both normal and infection-induced labor." (PMID 28386088, 2017). "To further determine whether inflammasome activation can be rescued in infected MyD88-/- BMM by addition of IFNβ, we treated BMM from WT and MyD88-/- mice with or without IFNβ followed by IOE infection, and measured levels of IL-1β." (PMID 29049365, 2017). "To investigate whether the NLRP7 inflammasome plays a role in the production of TNF-α and CCL3 besides IL-1β and IL-18, we silenced NLRP7 or ASC in THP-1 macrophages prior to infection, which significantly attenuated M. bovis-induced upregulation of TNF-α, CCL3 and IL-1β at the mRNA level." (PMID 27043315, 2016). "The molecules that depicted significant increases in those mAb treated-mice at 96 h after infection were CXCL1 (KC), CCL2 (MCP-1), CCL3 (MIP-1α), CCL4 (MIP-1β), CXCL2 (MIP-2), CXCL5 (LIX), IL-1α, IL-6, G-CSF, M-CSF, and TNF-α (for all, P < 0.01) and IL-1β, IL-15, IL-10, and LIF (for all, P < 0.05)." (PMID 27642235, 2016). "By correlating the pain thresholds with the cytokines levels time courses as well as the treatment period, it was concluded that IL-1β and IL-6 do not play a direct role and that other mediators are involved in L. major induced hyperalgesia at least during later stages of the infection." (PMID 26913003, 2016). "Since macrophages can release IL-1β in response to GBS, it is likely that they also play a role in the production of this cytokine, particularly after 24 h from the beginning of infection, when these cells start to be efficiently recruited to the infection site." (PMID 27509078, 2016). "The expression of IL-1β in the embryo tail fin was not related to the experimental infection because GFP is constitutively expressed in Tg(Il-1b:GFP-F+/+) embryos after 50 h post fertilization in keratinocytes at the tip of the caudal fin and in fin buds, retina, neuromasts, gills, and thymus." (PMID 27540375, 2016). "Over the time course IL1B expression was also higher in response to inactivated S. Typhimurium (P = 0.014), although this difference was not significant at any single time point post infection." (PMID 27000047, 2016). "Infection with the tonB strain did not enhance secretion of IL-1β or MIP-3α compared to the entB ybtS tonB mutant, suggesting that the differences between the level of induction by the WT strain and the level of induction by the entB ybtS strain were attributable to differences in bacterial density." (PMID 27624128, 2016). "However, non-TNFα-related mechanisms (e.g. through IL1β, TLR4 etc.)could still be able to control progress of the infection, and the net result is decreased pathogenicity." (PMID 27663205, 2016). "After KEI 1025 infection, GLY treatment reduced HMGB1 (mRNA and protein levels) and improved disease outcome with significant reduction in mRNA levels of IL-1β, TLR4, CXCL2, and IL-12; protein expression (IL-1β, CXCL2); neutrophil infiltrate; and bacterial load." (PMID 27792814, 2016). "Additionally, we have discussed both canonical and non-canonical processing of IL-1β induced with respect to particular infections." (PMID 27994587, 2016). "Thus, the antiviral activity of R848 in a single-cycle of infection was not mediated by IFNα or IL-1β." (PMID 27905985, 2016). "The κ-carrageenan could decrease the IL-6 and TNF-α mRNA levels but promote the IL-1β mRNA synthesis with or without SW731 infection." (PMID 25969984, 2015). "Infection of THP-1 cells with Leishmania did not induce IL-1β release as shown for L. mexicana." (PMID 26114647, 2015). "Moreover, this treatment increased the production of IL-12, IL-23, IL-27, IL-15, and IL1β such that negative correlations between the levels of these cytokines with both the infection ratio and number of intracellular parasites were observed." (PMID 26488744, 2015).
infection (continued). "Infections with amastigotes led to IL-1β maturation while promastigotes did not." (PMID 26114647, 2015). "Obviously, recombinant mouse IL-1β protein (20 ng/ml) is able to significantly induce Bgp1 expression in PEMs and RAW264.7 cells in vitro, and in concurrence, IL-1β treated RAW264.7 cells appear to produce more virus than the PBS treated controls post-infection." (PMID 26367131, 2015). "Because the absence of NleA resulted in higher IL-1β secretion by macrophages, this might implicate a more efficient inflammatory response from host cells at early stages of infection to increase the clearance of bacteria." (PMID 26332984, 2015). "TLR9-/- AMs infection with the ΔPscf mutant induced both TNFα and IL-6 but failed to induce IL-1β." (PMID 24595157, 2014). "Pre-infection plasma from the same individuals did not induce IL-18 or IL-1β." (PMID 24788318, 2014). "We observed that a number of NF-κB inducible genes were significantly elevated at 4 weeks post-infection (but not at 2 weeks) by qRT-PCR in B6 miR-146a−/− joints, compared to WT, including cytokines IL-1β and IL-6, as well as neutrophil chemokines Cxcl1 and Cxcl2." (PMID 24967703, 2014). "In contrast, SchuS4 infection did not induce cleavage of caspase-1 or secretion of IL-1β." (PMID 25191316, 2014). "During S. Typhimurium infection IL-1β is reported to be critical for the intestinal phase of the disease, while IL-18 is important for resistance to systemic infection but not the early gastrointestinal phase of infection." (PMID 25115174, 2014). "Furthermore, combining IL-1β or TNF-α with IFN-γ (100 ng/mL) reduced infection to control levels, similar to that of IFN-γ alone (data not shown)." (PMID 24259385, 2014). "Notably, infection of human MDM with M. bovis BCG did not induce significant differential expression of IFN-related genes or IL-1B secretion." (PMID 25414700, 2014). "The upregulation of IL-1β by 1α,25(OH)2D3 is also relevant for infection-induced inflammation, as in THP-1 cells or primary human macrophages infected with Mycobacterium tuberculosis (as well as in non-infected controls), 1α,25(OH)2D3 increased the expression of IL-1β mRNA." (PMID 25071589, 2014). "Furthermore, the lack of the P2X7R during MP287/03 Mbv infection did not affect the low production of IL-1β by lung infiltrating cells, but it restored the CD4+ and CD8+ T cell responses with the secretion of more IFNγ and less IL-10." (PMID 24991816, 2014). "IL-1β and IL-18 play an important role in local immunity and in the activation of lymphocytes and macrophages in the antiviral response, while IL-18 is mainly involved in coordinating IFN-γ production from NK cells and T cells at the early and late phases of infection, respectively." (PMID 24701032, 2014). "Hence, the increased expression of IL-6, IL-1β and CCL2 at later stages of infection may act to promote osteoclastogenesis." (PMID 25407789, 2014). "In addition, knockdown of Naip2, but not Naip5, reduced the release of IL-1β and IL-18 induced by Shigella infection at 1 or 2 hrs post-infection." (PMID 24516390, 2014). "Increased IL-1β expression was observed in the LP during acute pathogenic SIV, but not during non-pathogenic infection, suggesting that Caspase-1 activity could be a mediator of lentivirus pathogenesis." (PMID 24495380, 2014). "It is conceivable that the differential regulation of IL-1β by type I IFNs in non-immune versus immune cells reflects the different functions of type I IFNs, which are both antiviral and regulatory during the early infection of lung epithelial cells." (PMID 23592984, 2013). "No changes in the expression of intestinal IL-1β and IL-6 were observed at day 2 post infection." (PMID 24340048, 2013). "Neither infection status nor fetal viability affected placental expression of IL-1β." (PMID 23870389, 2013). "In contrast, Nlrp3−/− and ASC−/− mice had little to no IL-1β produced after infection." (PMID 24453428, 2013).